RAC1 (Rac family small GTPase 1)
Diseases named in the same sentence as RAC1 in open-access papers (continued):
Sharing a sentence is not in itself a finding about the gene and the disease.
tumor (continued). "In contrast, somatic mutations in tumor-promoting genes (FGFR1, RAC1, AFF3, AFF4, TSC2) may be intuitively associated with unfavorable prognosis." (PMID 30662871, 2018). "Tumors which express little RAC1b or maintain a low RAC1b:RAC1 ratio may become more aggressive and metastatic due to a preponderance of tumor-promoting RAC1." (PMID 28499439, 2017). "Regulation of UV-light-induced DDR by Rac1 may be connected to its tumor suppressive function in the epidermis." (PMID 28277539, 2017). "Furthermore, Rac1 also promotes tumor angiogenesis by inducing new vessel formation, and up-regulates the expression of HIF-1α and NF-κB, two major redox-dependent transcription factors induced by hypoxia environment." (PMID 28160553, 2017). "Our study is the first report presenting that RAC1-activation via beta-catenin-VAV2/TIAM1 cascade acts as a downstream signaling event of WP activation in TNBC in the regulation of fibronectin-directed MA tumor cell phenotypes." (PMID 27902969, 2017). "Rac1 activation is a required for Ras-mediated tumor progression." (PMID 28874189, 2017). "Interestingly, RAC1 was also found to be upregulated in CAFs in the primary tumor and in those residing in lymph node metastatic sites." (PMID 28499439, 2017). "In the light of the crucial roles of both TGF-β and RAC1 in tumor growth and various stages of the metastatic process, it was not unexpected that RAC1 can also transduce signals from other receptors, e.g. those for TGF-β which have serine/threonine kinase activity." (PMID 28499439, 2017). "Our findings lead to the hypothesis that Lu/BCAM, in the presence of laminin, can undergo ErK-RhoA/Rac1 signaling pathway to promote F-actin rearrangement and increase tumor cell adhesion and decrease cell migration." (PMID 28841878, 2017). "Therefore, the aim of this study was to investigate the effect of hypoxia on the expression of HIF-1α, RhoA, cdc42 and Rac1, RhoA activation, cell proliferation and migration using five tumor cell lines of different tissue origin." (PMID 28562340, 2017). "Importantly, both depletion of Rac1 and chemical inhibition was shown to antagonize the aggressive tumor-like properties of fibroblast-like synoviocytes." (PMID 27442895, 2017). "We report for the first time that RAC1-activation via beta-catenin-TIAM1/VAV2 cascade acts as a downstream signaling event of WP activation in TNBC in the regulation of fibronectin-directed MA tumor cell phenotypes." (PMID 27902969, 2017). "RAC1-induced reactive oxygen species (ROS) generation might facilitate IMP2-induced tumor progression." (PMID 29163784, 2017). "As migration occurs following an alteration of the adhesive property of cells and migration is required for tumor cell invasion and eventually metastasis, we tested the involvement of RAC1 downstream of WP pathway activation in the integrin-directed migration of TNBC cells." (PMID 27902969, 2017). "Rac1 activation also directly activates the JNK pathway leading to tumor progression." (PMID 28874189, 2017). "Based on their opposing effects, alterations in the ratio of RAC1b:RAC1 expression and/or activity may thus represent a potential tool for the tumor to modulate net TGF-β1 signaling activity." (PMID 28499439, 2017). "Accordingly, we measured the proliferation, migration, RhoA activation, the mRNA and protein levels of hypoxia inducible factor-1alpha (HIF-1α) and three small G-proteins, Rac1, cdc42 and RhoA in a panel of five human tumor cell lines under normoxic and hypoxic conditions." (PMID 28562340, 2017).
tumor (continued). "Data from a K-rasG12D murine model with pancreas-specific ablation of RAC1 suggested that the protein product(s) of RAC1 is a crucial mediator of TGF-β/K-Ras-driven tumourigenesis since it prevented tumour development and significantly prolonged survival in these mice." (PMID 29229918, 2017). "The observed difference in the number of γH2AX positive cells in the tumor samples between different mouse groups may indicate an inhibited DNA damage response in the skin of K14 HPV-8/Rac1-EKO mice." (PMID 27506937, 2016). "Here, we demonstrated that β6 promoted tumor cell malignant behaviors by activating Rac1." (PMID 27440504, 2016). "Furthermore, TIPE2 suppressed tumor invasiveness and angiogenesis via inhibiting the activation of Rac1 and subsequently weakening its downstream effects, including F-actin polymerization and VEGF expression." (PMID 27556698, 2016). "Finally, Knockdown of MST3 or Rac1 inhibitor decreases cyclin D protein expression, which is important for tumor growth." (PMID 26910843, 2016). "Based on these results, it could be concluded that icariin inhibit the tumor cell invasion and migration through the Rac1-dependent VASP pathway." (PMID 27649234, 2016). "In addition, cell cytoskeleton rearrangements are regulated by Rac1 and provide a critical process for the invasive and metastatic spread of tumor cells." (PMID 27231134, 2016). "Given that the mesenchymal mode of motility requires extracellular proteolysis, whereas the amoeboid mode is independent of proteases 5, the two interconvertible modes may participate in tumor progression and invasion in GBMs through the FilGAP/Rac1 axis." (PMID 27790861, 2016). "Interestingly, hypoxia was found to increase FAK phosphorylation, Rac1 activity and tumor cell migration in a Rab5-dependent manner." (PMID 27121131, 2016). "Moreover, TIPE2 suppressed tumor invasiveness and angiogenesis via inhibiting the activation of Rac1 and subsequently weakening its downstream effects, F-actin polymerization and VEGF expression." (PMID 27556698, 2016). "The discovery that anti-CD99 0662mAb exerts its anti-tumor action by enhancing IGF-1R/RAS/Rac1 activity may seem paradoxical." (PMID 27835596, 2016). "In R3327-5′A rat tumour cells that had Ccnd1 downregulated by RNA interference, activated Rac1 levels depended on Ccnd1 because transfecting these cells with human Ccnd1 restored the wild-type levels of activated Rac1." (PMID 27181366, 2016). "In addition, the existence of a Ccnd1·Cdk4-Pxn-Rac1 axis helps explain the invasive properties of tumours overexpressing Ccnd1." (PMID 27181366, 2016). "This HA-induced Rac1 activity leads to enhanced astrocyte migration and promotes tumor progression." (PMID 27163367, 2016). "Rac1 has a number of well-characterized functions in the movement of both normal and tumor cells, traditionally shown to be important for actin polymerization to drive lamellipodia-based movement and the formation of invadopodia to facilitate matrix proteolysis." (PMID 27589803, 2016). "However, studies have shown that Rac1 activation is a pre-requisite for Ras-mediated tumor progression." (PMID 27629044, 2016). "These researches suggest that signals from REPS2 might suppress tumor growth and metastasis through RalBP1/RAC1/CDC42 signaling pathway." (PMID 27120794, 2016). "However, activation of Rac1 can lead to opposing migratory phenotypes raising the possibility of exacerbating tumour progression when targeting Rac1 in a clinical setting." (PMID 26887924, 2016). "The other RhoGTPases that have been shown to contribute to tumor progression are Cdc42 and Rac1." (PMID 27597870, 2016). "Thus, deletion of one copy of Rac1 in endothelium markedly attenuates the endothelial permeability and hematogenous metastasis of tumor cells to lungs." (PMID 25991673, 2015). "Here, we determine whether tumor-secreted vasoactive stimulant through Rac1 inducing permeability contributes to hematogenous metastasis." (PMID 25991673, 2015).
tumor (continued). "Rac1 has an essential role in tumour cell proliferation and survival." (PMID 26133397, 2015). "Moreover, we have managed to identify the role of endothelial Rac1 in tumor metastasis by using a murine model of hematogenous metastasis to lung." (PMID 25991673, 2015). "This incomplete inhibition of tumor metastasis following Rac1-inhibition may be the result of a compensatory activation of Tβ4-mediated Rap1, suggesting that both Rac1- and Rap1-GTPase activity may be regulated by Tβ4." (PMID 25888632, 2015). "We found that Tβ4 activated both Rap1 and Rac1 in tumor cells." (PMID 25888632, 2015). "However, numerous studies have shown the conflicting role of RhoGDI2 in the regulation of Rac1 dependenting on the tumour types and/or cellular microenvironment." (PMID 25901126, 2015). "Future work will be required to determine the biochemical details of this process, such as the role of Rac1, and to test whether the observed mutual exclusivity of other combinations of mutant genes in other tumor types are attributable to such mechanisms." (PMID 26047463, 2015). "Simultaneous inhibition of Rap1 and Rac1 may therefore represent an effective therapeutic strategy for inhibiting tumor cell motility." (PMID 25888632, 2015). "More importantly, overexpression of RAC1 in HCC cells could abolish the effect of MVs on the migration of tumor cells." (PMID 25292173, 2014). "In tumor tissues of patients, Rac1 activation is positively correlated with keratin 17 expression." (PMID 24962779, 2014). "As a target of miR-142-3p, RAC1 plays a key role in tumor cell growth, migration and invasion." (PMID 25292173, 2014). "Moreover, the level of miR-100 was negatively related to the expression of ICMT and Rac1 in tumor tissues." (PMID 25361001, 2014). "Our findings suggested the mechanism of tumor promotion by Rac1 in this process." (PMID 24962779, 2014). "Based on our observations we hypothesize that tumour cells under such conditions are forced to carefully balance Rac1b to Rac1 expression and activity." (PMID 24378395, 2014). "Our results suggest that miR-100 simultaneously represses two molecules in the Rac1 signaling pathway, which may provide a more effective prevention for tumor metastasis." (PMID 25361001, 2014). "Furthermore, Rac1 is overexpressed in AIDS-KS lesions and in KSHV-infected mECK36 tumors, and the antioxidant NAC was able to completely suppress Rac1-induced tumor formation in RacCA transgenic mice." (PMID 24708874, 2014). "A recent study suggests that TGF-β/K-ras-mediated tumourigenesis is crucially mediated by the monomeric GTPase Rac1, since deletion of Rac1 from the pancreas in a K-rasG12D murine model prevented the formation of K-ras-driven tumours and significantly prolonged survival." (PMID 24378395, 2014). "Tumor cells may overproduce ROS because the NADPH-oxidase is regulated by the GTPase Rac1, which is itself downstream of the proto-oncogene Ras." (PMID 23947403, 2013). "Moreover, the subcutaneous xenograft of the tumor cells in NSG mice showed that the RAC1 knockdown cells had delayed tumor development and reduced tumor volume compared with the control cells." (PMID 24146998, 2013). "Tumor cell migration is often associated with the occurrence of an epithelial-to-mesenchymal transition (EMT), and the activation of the small GTPases Rho, Cdc42 and Rac1." (PMID 23894465, 2013). "Thereby, control of cell-cell contact to maintain cells as a cohesive epithelium and regulation of cell migration to favours invasion could be considered as two antagonistic effects of Cdc42 and Rac1 on tumour progression." (PMID 23144867, 2012). "These two modes of movement are inter-convertible and tumour cells may undergo amoeboid-mesenchymal and mesenchymal-amoeboid transitions that seem to be controlled by an antagonism between the Rac1 and RhoA signalling pathways." (PMID 23144867, 2012).
tumor (continued). "In addition, subcutaneous xenograft of the tumor cells (500,000 cells/mouse) in NSG mice established that Rac1 knockdown cells had delayed tumor development and reduced tumor volume compared with the control cells." (PMID 21347385, 2011). "Finally, Rac1 shRNA was effective in suppressing the primary tumor cell colonization in lung compared to Scr control." (PMID 21347385, 2011). "Both A549 and H441 cells expressing Scr (500,000 cells/mouse) caused tumor formation in the lungs while Rac1 knockdown cells (500,000 cells/mouse) failed to form tumors in the lungs 8 weeks post-injection." (PMID 21347385, 2011). "Also TGF-β and Rac1 signalling exert antagonistic roles in tumour cell proliferation but share common nuclear targets such as cyclin D1 and p21WAF1." (PMID 21624123, 2011). "We have shown that the chemokine CCL2 induces tumor cell diapedesis via Rac1 activation." (PMID 21776386, 2011). "The chemokine CCL2 is produced by BMECs and stimulates Rac1-mediated tumor cell diapedesis." (PMID 21776386, 2011). "Furthermore, hydrogen peroxide which is generated as a metabolic product of LOX activity, stimulates activity of the small GTPase Rac1 and thereby enhances the migratory/invasive behavior of tumor cells." (PMID 21914164, 2011). "Our current study adds to this list of potential CSC targeting approaches by presenting evidence that Rac1 inhibition could be efficacious for suppressing both tumor initiation and metastasis of NSCLA CSCs." (PMID 21347385, 2011). "Rac1-mediated epithelial migration of the AVE is a crucial step in the establishment of the mammalian body plan, and Rac1 may be important for collective migration in general in mammalian tissues, including invading tumor cells." (PMID 20689803, 2010). "Endothelial cell proliferation, migration and tube formation are essential processes during tumor angiogenesis and Rac1 activity is believed to be important for these cellular processes in vitro implying a possible requirement for this molecule in angiogenesis in vivo." (PMID 20339539, 2010). "We investigated the correlation between Rac1 activity and Pak1 expression in tumor tissues." (PMID 20426825, 2010). "Our findings suggest that inhibition of Rac1 might be an effective anti-angiogenic therapeutic strategy in tumor blood vessels that display low levels of β3-integrin." (PMID 20339539, 2010). "Given the enhanced pathological angiogenic responses in β3-null mice we asked whether endothelial Rac1 was differentially required in tumor angiogenesis in adult wild-type or β3-null mice." (PMID 20339539, 2010). "The possiblelink between apocynin and Rac1 inhibition suggests that apocynin may be asource for inhibitors of Rac1-mediated tumor cell migration." (PMID 19096513, 2008). "The contribution of Tiam1-mediated activation of Rac1 to the upregulation of such tumour-promoting genes may represent one mechanism by which the Tiam1/Rac1 signalling module contributes to tumour development in the colon." (PMID 18826597, 2008). "Rac1 and RhoA were antagonistic regulators of both basal and stimulated tumour cell NHE1 activity." (PMID 15535843, 2004). "Accordingly, the questions are whether RhoA and Rac1 reciprocally regulate motility in tumour cells of epithelial origin, and if so then do they act via a coordinated regulation of NHE1 activity?" (PMID 15535843, 2004). "Furthermore, the tumour specific increase in rac1 mRNA expression reported in this study was rather low (i.e. ∼50%) and does not reflect the large increase in Rac1 protein expression observed in the tumours." (PMID 12237774, 2002). "In this report, we found that Nischarin (NISCH), established as a tumor suppressor, is susceptible to S-glutathionylation, selectively at Cys185 located near its leucine-rich repeat (LRR) domains, which are implicated in protein-protein interactions with Rac1 and PAK1." (PMID 41213437, 2025).
tumor (continued). "In addition, Axl activation may trigger actin remodelling via Rac1 and affect FA turnover and cell spreading which leads to tumour cell migration and invasion." (PMID 39779468, 2025). "Given that our study suggests a potential negative correlation between RAC1 expression levels and B cell infiltration in the tumor microenvironment, it is hypothesized that jointly evaluating RAC1 gene expression and B cell infiltration may offer valuable insights for predicting patient prognosis." (PMID 39898257, 2025). "However, tumor growth was restored when the RAC1 pathway was inhibited by EHop-016." (PMID 38706891, 2024). "Having a buffer for RAC1 activity could provide advantages for tumours, where mutations in KRAS will drive high activation of RAC1, which might be detrimental to cell survival due to enhanced reactive oxygen species production and enhanced downstream signalling." (PMID 38712822, 2024). "Furthermore, p120 downregulation may lead to tumor progression and metastasis by reducing β-catenin and E-cadherin expression, and altering the activities of Cdc42, Rac1 and RhoA." (PMID 39498333, 2024). "Although the role of Rac1, one of the small G-proteins, in hypoxia remains unclear, predominantly, in vitro studies performed so far confirm that Rac1 inhibition may represent a viable direction for tumor therapy." (PMID 38791951, 2024). "Rac Family Small GTPase 1 (RAC1), a well-defined oncoprotein in NSCLC, drives its malignant progression by enhancing the proliferation, migration, and invasion abilities in tumor cells, which may be implicated in the RAC1-mediated activation of the MAPK/ERK and PI3K/AKT oncogenic signaling pathways." (PMID 39164746, 2024). "Finally, through animal experiments, we found that PF could significantly inhibit tumor formation by OC cells and reverse the tumor‐promoting effect of RAC1 overexpression." (PMID 39224538, 2024). "Thus, targeting Rac1-Scar/Wave-Arp2/3 would help to inhibit tumor progression." (PMID 37049739, 2023). "ENO1 and RAC1 also showed high levels of expression in EGFR mutant LUADs aligning with previous studies demonstrating that ENO1 expression is greater in LUAD tumor samples relative to non-cancerous tissue, and the RAC1 splice variant RAC1B enhances LUAD tumor formation in vivo." (PMID 38260835, 2023). "However, introducing the expression of RAC1CA, but not RAC1WT, restored the tumor formation ability of the RAB4A knockdown cells to the level of control cells, which is consistent with the notion that RAC1 is the primary mediator of RAB4A regulation of tumor formation and progression." (PMID 36307864, 2022). "Moreover, our results demonstrate that LAPTM5 activates the Jun N-terminal kinase (JNK)/p38 axis by binding to Ras-related C3 botulinum toxin substrate 1 (RAC1), and the effects of LAPTM5 on tumor growth were attenuated following treatment with an RAC1 inhibitor." (PMID 36385959, 2022). "In summary, our study supported that Rac1 inhibition could protect normal lung tissue from, and at the same time, sensitize lung tumors to radiation-induced damage, making it an important target for clinical radiation protection and tumor radiotherapy." (PMID 35031595, 2022). "Notably, targeting of Rac1 by depletion of specific Rac-guanine nucleotide exchange factors (Rac-GEFs) fails to hinder the tumor growth in the presence of KRAS mutations, limiting its clinical use for advanced tumors." (PMID 35158939, 2022). "Thus, the three drugs target signalling elements upstream of Rac1 and show acceptable tolerability in clinical studies in addition to anti‐neoplastic activity in different tumour types including advanced renal cell carcinoma, hepatocellular carcinoma and solid tumours." (PMID 36377725, 2022).